AMY1B (amylase alpha 1B)
Description:
Calcium-binding enzyme that initiates starch digestion in the oral cavity. Catalyzes the hydrolysis of internal (1->4)-alpha-D-glucosidic bonds, yielding a mixture of maltose, isomaltose, small amounts of glucose as well as small linear and branched oligosaccharides called dextrins.
Synonyms: AMY1
Tractability: Small molecule: it belongs to a druggable protein family. Antibody: UniProt places it where antibodies can reach, with high confidence; UniProt predicts a signal peptide or a membrane-spanning region; its Gene Ontology location is reachable by antibodies, with medium confidence.
Gene: Protein-coding gene on chromosome 1 (103,687,415 to 103,701,064, reverse strand). Ensembl gene ENSG00000174876.
Subcellular location: Secreted
Subcellular location (Human Protein Atlas): Cytosol; Golgi apparatus; Predicted to be secreted
Pathways (Reactome):
Digestion and absorption: Digestion of dietary carbohydrate
Gene Ontology:
Molecular function: alpha-amylase activity; calcium ion binding; chloride ion binding; catalytic activity; cation binding
Biological process: oligosaccharide metabolic process; carbohydrate metabolic process
Cellular component: extracellular exosome; extracellular region
Homologues: Orthologues: macaque AMY2B (94% identical), tropical clawed frog amy2a (77% identical), tropical clawed frog amy2b (75% identical), Drosophila melanogaster Amy-p (53% identical), Drosophila melanogaster Amy-d (52% identical), Caenorhabditis elegans C50B6.7 (47% identical), Drosophila melanogaster Amyrel (47% identical), Drosophila melanogaster Mal-A7 (16% identical), Drosophila melanogaster Mal-A4 (15% identical), Drosophila melanogaster Mal-B2 (14% identical), Drosophila melanogaster Mal-A2 (14% identical), Drosophila melanogaster Mal-A8 (14% identical), and 3 more. Paralogues in human: AMY1A (100% identical), AMY1C (100% identical), AMY2B (97% identical), AMY2A (97% identical), SLC3A1 (17% identical), GBE1 (15% identical), SLC3A2 (13% identical).
Diseases named in the same sentence as AMY1B in open-access papers:
AMY1B is named in the same sentence as 2 diseases in open-access papers, as found by Europe PMC text mining. Sharing a sentence is not in itself a finding about the gene and the disease.
AMY1B shares sentences with these, for which no sentence is quoted: breast carcinoma (1 paper); tumor (1).